CDH18 (cadherin 18)
Description:
Cadherins are calcium-dependent cell adhesion proteins. They preferentially interact with themselves in a homophilic manner in connecting cells; cadherins may thus contribute to the sorting of heterogeneous cell types.
Synonyms: CDH14; EY-CADHERIN
Tractability: Antibody: its Gene Ontology location is reachable by antibodies, with high confidence; UniProt places it where antibodies can reach, with medium confidence; UniProt predicts a signal peptide or a membrane-spanning region. PROTAC: ubiquitination databases record sites on it.
Gene: Protein-coding gene on chromosome 5 (19,471,296 to 20,575,873, reverse strand). Ensembl gene ENSG00000145526.
Subcellular location: Cell membrane
Pathways (Reactome):
Cell-Cell communication: Adherens junctions interactions
Gene Ontology:
Molecular function: beta-catenin binding; cadherin binding; calcium ion binding
Biological process: adherens junction organization; calcium-dependent cell-cell adhesion; cell migration; cell morphogenesis; cell-cell adhesion mediated by cadherin; cell-cell junction assembly; cell adhesion; cell-cell adhesion; homophilic cell-cell adhesion
Cellular component: adherens junction; catenin complex; plasma membrane; membrane
Genetic constraint (gnomAD): Loss-of-function variants: 26 observed, 48.97 expected, observed/expected ratio (o/e) 0.53, 90% interval 0.39 to 0.74. The upper end of that interval is the gene's LOEUF score, 0.74, which puts it in group 3 of 6, group 1 being the genes least tolerant of losing a copy. Missense variants: 713 observed, 823.87 expected, observed/expected ratio (o/e) 0.87, 90% interval 0.81 to 0.92. Synonymous variants: 294 observed, 297.14 expected, observed/expected ratio (o/e) 0.99, 90% interval 0.9 to 1.09.
Homologues: Orthologues: chimpanzee CDH18 (99% identical), macaque CDH18 (99% identical), pig CDH18 (98% identical), dog CDH18 (97% identical), rabbit CDH18 (97% identical), rat Cdh18 (97% identical), mouse Cdh18 (96% identical), guinea pig CDH18 (91% identical), tropical clawed frog cdh18 (84% identical), zebrafish CDH18 (71% identical), zebrafish cdh18a (7% identical). Paralogues in human: CDH7 (60% identical), CDH10 (58% identical), CDH11 (58% identical), CDH12 (57% identical), CDH9 (57% identical), CDH20 (57% identical), CDH6 (56% identical), CDH8 (55% identical), CDH22 (51% identical), CDH24 (50% identical), CDH19 (46% identical), CDH5 (39% identical), and 21 more.
Diseases named in the same sentence as CDH18 in open-access papers:
CDH18 is named in the same sentence as 47 diseases in open-access papers, as found by Europe PMC text mining. Sharing a sentence is not in itself a finding about the gene and the disease. The quoted sentences say what the papers report.
glioma (7 papers, 2020 to 2025). A benign or malignant brain and spinal cord tumor that arises from glial cells (astrocytes, oligodendrocytes, ependymal cells). "Some studies reported the association between CDH18 gene and congenital heart diseases, diabetes mellitus, and glioma." (PMID 34980134, 2022). "Studies have shown that lower levels of CDH18 increase glioma cell invasion and migration, whereas higher expression reduces glioma cell resistance to chemotherapy." (PMID 40017628, 2025). "The iTRAQ-based quantitative analysis showed that CDH18 was downregulated in tumor tissue from patients with glioma, and its downstream target, UQCRC2, was down-regulated in tumor tissue from patients with glioma compared to healthy tissue." (PMID 34631760, 2021). "The role of CDH18 in glioma carcinogenesis and its progression examined using proteomic analysis based on their group cohort database." (PMID 34631760, 2021). "On the other hand, UQCRC2 can inhibit glioma progression as it mediates the effect of cadherin 18 on suppressing the invasion of glioma cells." (PMID 34361072, 2021). "For example, CDH18 was shown to inhibit invasion/migratory ability and chemoresistance via ubiquinol cytochrome c reductase core protein 2 (UQCRC2) in gliomas,and reduce malignancy in gastric cancer via the constitutive photomorphogenesis 1 (COP1)-PI3K/AKT pathway axis." (PMID 40017628, 2025). "In addition, there is no report about CACNG2, JPH3, TUBB6 (tubulin β 6 class V), NRSN1, FAM19A2, NALCN, CDH18, GNAL on glioma." (PMID 32406502, 2020).
depression (5 papers, 2020 to 2024). "Various studies have demonstrated that genetic abnormalities in CDH18 are associated with various neuropsychiatric disorders, such as bipolar disorder, schizophrenia, depression, and autism, as well as cancers, such as colorectal cancer and ovarian cancer." (PMID 39081806, 2024). "Moreover, CDH18 was reported in a meta-analysis of depression personality trait association as the nearest gene to rs34947537." (PMID 31996736, 2020).
breast carcinoma (4 papers, 2018 to 2024). "Particularly, the negative association between the genes CDH2, CDH3, CDH11, CDH13, CDH18 and NAT1 N-acetylation activity supports observations of high NAT1 expression in breast cancer and increased metastasis." (PMID 35046826, 2021).
schizophrenia (4 papers, 2018 to 2024). A major psychotic disorder characterized by abnormalities in the perception or expression of reality. "CDH7 and CDH12 have been associated with bipolar disorders and CDH18 was found to be associated with schizophrenia." (PMID 39570883, 2024). "Moreover, a group of cadherins, CDH7, CDH12, CDH18 and PCDH12, are reported to be associated with bipolar disease and schizophrenia." (PMID 30148849, 2018).
gastric cancer (3 papers, 2023 to 2025). A primary or metastatic malignant neoplasm involving the stomach. "CDH18 expression is upregulated when constitutive photomorphogenesis 1 (COP1) is silenced, which promotes gastric cancer development by failing to inhibit PI3K/AKT signaling." (PMID 40017628, 2025).
metabolic syndrome (3 papers, 2019 to 2024). A cluster of metabolic risk factors for CARDIOVASCULAR DISEASES and TYPE 2 DIABETES MELLITUS. "Given the increased propensity for PCOS affected women to develop T2DM, and the associated metabolic syndrome type clinical features, it is possible that CDH18 has some link to PCOS, particularly overweight/obese PCOS." (PMID 38408933, 2024). "Additional dmCpG in regulatory regions of pathobiologically relevant genes included PA-dmCpG within the ACBD5 that is involved in long-chain FA metabolism; CD34, an adipocyte progenitor marker; and CDH18 that hosts variants associated with the metabolic syndrome." (PMID 34025721, 2021). "Notably, genetic variation at the CDH18 locus has been associated with metabolic syndrome-related traits before." (PMID 30852652, 2019).
Alzheimer disease (2 papers, 2020 to 2023). A progressive, neurodegenerative disease characterized by loss of function and death of nerve cells in several areas of the brain leading to loss of cognitive function such as memory and language. "CTNNA2 has previously been associated with a number of phenotypes, including Alzheimer disease and blood pressure, whereas CDH18 has similarly been associated with blood pressure traits, including hypertension." (PMID 32889533, 2020).
autism spectrum disorder (2 papers, 2021). A spectrum of developmental disorders that includes autism, and Asperger syndrome. "Structural variations of CDH18 are associated with autism spectrum disorders." (PMID 34380431, 2021).
endometrial cancer (2 papers, 2023 to 2025). Primary or metastatic malignant neoplasm involving the endometrium (mucous membrane that lines the endometrial cavity). "Although there have been limited studies on CDH18 in the context of endometrial cancer, its connection with macrophages presents an intriguing direction for further exploration." (PMID 37780629, 2023). "The correlation of CDH18 with macrophage M0 cells may indicate its significant role in tumor differentiation and prognosis in endometrial cancer." (PMID 37780629, 2023). "Investigating CDH18’s expression, function, and regulation within the tumor might reveal novel insights into endometrial cancer differentiation, providing valuable prognostic information and possibly unveiling new therapeutic targets." (PMID 37780629, 2023). "The results confirmed a positive correlation of CDH18 expression in HEC-1-B endometrial cancer cell lines compared to HEEC of non-cancer cells." (PMID 40017628, 2025).
Obesity (2 papers, 2019 to 2025). Accumulation of substantial excess body fat. "In previous GWAS, variants of the CDH18 gene were found to be associated with leprosy, age-related hearing impairment, blood pressure-related traits in African-Americans and with obesity in adult survivors of childhood cancer." (PMID 30852652, 2019). "In another study, a GWAS conducted on 1996 adult CCS (median age at diagnosis, 7.2 years; median age at follow-up, 32.4 years) identified potential obesity-associated loci on chromosomes 13 (FAM155A), 2 (SOX11), 4 (GLRA3), and 5 (CDH18, BASP1), particularly among CRT-exposed survivors." (PMID 41228239, 2025).
cervical cancer (1 paper, 2013). A primary or metastatic malignant neoplasm involving the cervix. "Among the 49 PRC2 targets (defined by consistent hyper-MVPs) identified here were 10 genes of the cadherin superfamily in HPV+ HNSCC, including CDH8 and CDH13 (both also hypermethylated in cervical cancer, CDH18, CDH19, CDH23, PCDH10, PCDH15, PCDHB1, PCDHB4, and PCDHB15." (PMID 23419152, 2013).
cholesteatoma (1 paper, 2012). A pathologic process characterized by the proliferation of keratinizing squamous epithelium resulting in the accumulation of keratin and cells in the middle ear and/or mastoid. "We were able to demonstrate that two integral membrane proteins, CDH18 and CDH19, from the cadherin superfamily are down-regulated in cholesteatoma." (PMID 23285167, 2012). "Moreover, tumor suppressor genes CDH18, 19 and ID4, which are known to be down-regulated in various tumors PAX3, LAMC2 and TRAF2B are also down-regulated in cholesteatoma." (PMID 23285167, 2012).
colon cancer (1 paper, 2025). "KEGG pathway analysis indicated that CDH18-associated DEGs were predominantly linked to neuroactive ligand-receptor interactions, a pathway implicated in immunosuppression in colon cancer." (PMID 40017628, 2025).
glioblastoma (1 paper, 2023). The most malignant astrocytic tumor (WHO grade IV). "Lower expression of both FLNB and CDH18 have been shown to have anti-invasive effects in mouse embryonic fibroblasts and glioblastoma cells." (PMID 38033034, 2023).
Insulin resistance (1 paper, 2013). Increased resistance towards insulin, that is, diminished effectiveness of insulin in reducing blood glucose levels. "Variants of genes AKAP6, NPAS3, MARCH6 and FBXL7 have been previously reported to be associated with insulin resistance, inflammatory markers or adiposity studies using genome-wide approaches whereas associations of CDH18 and MYO10 with MetS traits have not been reported before." (PMID 23628382, 2013).
liposarcoma (1 paper, 2018). A usually painless malignant tumor that arises from adipose tissue. "However, all well-differentiated tumors were CDH18-positive, and because well-differentiated liposarcoma has a better prognosis than dedifferentiated liposarcoma, we reanalyzed the data after excluding well-differentiated samples." (PMID 29789718, 2018).
migraine (1 paper, 2021). "Overall, these studies support the potential effects of CDH18 on the mechanisms involved in migraine." (PMID 34380431, 2021).
non-small cell lung carcinoma (1 paper, 2018). A group of at least three distinct histological types of lung cancer, including non-small cell squamous cell carcinoma, adenocarcinoma, and large cell carcinoma. "Expression of CDH18 was lower in LS8107 and LS8313 cells and in the non-small cell lung cancer cell line H358, all of which fail to senesce following CDK4/6 inhibition." (PMID 29789718, 2018).
small cell lung carcinoma (1 paper, 2018). Small cell lung cancer (SCLC) is a highly aggressive malignant neoplasm, accounting for 10-15% of lung cancer cases, characterized byrapid growth, and early metastasis. "CDH18 protein was readily detected in LS8817, LS141, and LS0082 cells, and in the non-small cell lung cancer cell line H1975, all of which senesce following CDK4/6 inhibition." (PMID 29789718, 2018).
tumor (10 papers, 2012 to 2025). "Altogether, CDH18, as a calcium-related protein, appears to be closely linked to immune regulation in the tumor context." (PMID 40017628, 2025). "This study investigates the clinical significance and prognostic value of CDH18, a calcium-dependent adhesion protein linked to tumor progression, in UCEC." (PMID 40017628, 2025). "CDH18 is also significantly mutated in GBM tumours and encodes a cadherin protein involved in cell–cell adhesion." (PMID 26264438, 2016). "Based on these findings, we hypothesize that CDH18 may be associated with tumor progression and potentially influence UCEC prognosis, although further studies are needed to confirm its functional role." (PMID 40017628, 2025). "CDH18 promoter methylation differed between tumor and normal samples from TCGA, with 18 CpG sites showing increased DNA methylation." (PMID 40017628, 2025). "CDH18 is a novel promising biomarker in UCEC, uniquely associating tumor progression, immune modulation, and chemotherapy resistance, offering enhanced prognostic accuracy and guiding individualized therapeutic strategies for improved patient outcomes." (PMID 40017628, 2025). "Recent findings highlight an association between CDH18 and macrophages within the UCEC tumor microenvironment." (PMID 40017628, 2025). "In contrast, downregulated genes included at least 15 candidate tumor suppressors (e.g., CDH18, HEG1)." (PMID 41278279, 2025). "Immunofluorescence staining (IF) and Real-Time Polymerase Chain Reaction techniques (RT-PCR) confirmed CDH18 expression in UCEC tumor." (PMID 40017628, 2025). "The CDH18 gene, which exhibits specific expression levels across various tumor types and the central nervous system, was reported to be related to tumor progression." (PMID 40017628, 2025). "Conversely, CDH18 expression was inversely linked to CD8+ T cells, which are capable of suppressing tumor growth." (PMID 40017628, 2025). "Additional analyses included functional enrichment, tumor mutational burden, tumor microenvironment (TME) estimates via ESTIMATE, and immune infiltration assessment to clarify CDH18’s potential mechanisms in UCEC." (PMID 40017628, 2025). "CDH18 expression correlated positively with resting NK cells and M2 macrophages, both of which are known to inhibit anti-tumor immune responses." (PMID 40017628, 2025). "CDH18 expression was positively correlated with resting NK cells and M2 macrophages, which promote tumor angiogenesis, growth, and metastasis." (PMID 40017628, 2025). "To investigate the hypothesis that elevated CDH18 expression may contribute to tumor growth, we conducted a GSEA." (PMID 40017628, 2025). "Specifically, in UCEC samples, CDH18 expression was notably higher than in non-tumor tissues." (PMID 40017628, 2025). "Interestingly, CDH18 appears to play varied roles in tumor progression across different cancer types." (PMID 40017628, 2025). "It was observed that CDH18 levels were elevated in numerous tumor tissues." (PMID 40017628, 2025). "Furthermore, given CDH18’s involvement in tumor progression and chemotherapy resistance in other cancer types, we propose that CDH18 expression levels could serve as a prognostic marker in UCEC." (PMID 40017628, 2025). "Our data suggest that CDH18 and a deeper understanding of SAGA might also predict if cell lines or a patient’s tumor would be innately resistant or clinically sensitive to CDK4/6 inhibitors." (PMID 29789718, 2018). "In contrast, CDH18 showed negative correlations with TNFSF14, TNFSF15, PDCD1, TNFRSF14, and CD44, genes reported to play critical roles in tumor inhibition." (PMID 40017628, 2025).
cancer (6 papers, 2013 to 2025). A tumor composed of atypical neoplastic, often pleomorphic cells that invade other tissues. "Current studies on the direct association between CDH18 and immune cells or immune cell infiltration in cancer are relatively limited." (PMID 40017628, 2025). "The expression of the calcium associated protein-CDH18 was assessed using data from the TCGA database for various cancer types." (PMID 40017628, 2025). "Pan-cancer analysis, differential expression examination, and survival analysis were conducted to investigate the differential expression of the calcium associated protein-CDH18 and its prognostic relevance." (PMID 40017628, 2025). "A positive correlation was found between CDH18 and VTCN1, an immune checkpoint molecule associated with poor prognosis and cancer progression." (PMID 40017628, 2025). "This variability suggests that CDH18 may engage different pathways in different cancer contexts." (PMID 40017628, 2025). "However, prior studies have reported conflicting roles for CDH18 in different cancers." (PMID 40017628, 2025). "Thus it is possible that the CDH18 gene and other nearby genes identified in cohort (including CTNND2, CDH12 and MYO10) play a mechanistic role in the observed connection between MetS and cancer risk." (PMID 23628382, 2013). "In this study, the expression of the CDH18 gene, which was increased in the HG-ESS, differed in 13 cancer types." (PMID 38167455, 2024).
psychiatric diseases (2 papers, 2021 to 2024). "Cdh18 is a cell adhesion protein involved in synaptic adhesion and has been implicated in several psychiatric diseases." (PMID 38784708, 2024).
CDH18 also shares sentences with these, for which no sentence is quoted: autism (3 papers); bipolar disorder (3); ovarian carcinoma (2); age-related macular degeneration (1); apraxia (1); attention deficit-hyperactivity disorder (1); breast invasive carcinoma (1); childhood cancer (1); colorectal cancer (1); congenital heart disease (1); diabetes mellitus (1); esophageal cancer (1); hepatocellular carcinoma (1); Hypertension (1); Intellectual disability (1); leprosy (1); liver fibrosis (1); lung adenocarcinoma (1); lung squamous cell carcinoma (1); neurodegenerative disease (1); ovarian dysgenesis (1); paraganglioma (1); pheochromocytoma and (1); Speech apraxia (1); uterine corpus endometrial carcinoma (1).